LZTR1 (leucine zipper like post translational regulator 1)
Diseases named in the same sentence as LZTR1 in open-access papers (continued):
Sharing a sentence is not in itself a finding about the gene and the disease.
schwannomatosis (continued). "Additionally, incorporation of molecular criteria has been proposed, including detection of NF2 gene variants in the peripheral blood or in multiple tumors, and exclusion of patients with lesions harboring mutations in LZTR1 which are associated with schwannomatosis." (PMID 31161239, 2020). "Now the molecular mechanism of schwannomatosis is thought to consist of mutations in two genes SMARCB1 and LZTR1." (PMID 40337438, 2025). "Previous studies have implicated LZTR1 mutations in conditions such as glioblastoma (GBM), schwannomatosis (SWNMT), and Noonan syndrome (NS)." (PMID 38764094, 2024). "The LZTR1 gene, which also interacts with the RAS pathway, is associated with both NS and schwannomatosis." (PMID 39062695, 2024). "SWN is a clinical distinct entity as a result of germline NF2 (22q-related schwannomatosis), or SMARCB1 (SMARCB1-related schwannomatosis), or LZTR1 variant (LZTR1-related schwannomatosis), which are located centromeric to NF2 on chromosome 22." (PMID 37046591, 2023). "Schwannomatosis is an autosomal dominant disorder characterized by the development of multiple schwannomas, and it is caused by mutations in the SMARCB1 and LZTR1 genes." (PMID 37240461, 2023). "Dominant variants in LZTR1 have been associated with Noonan syndrome 10 (OMIM #616564) and Noonan syndrome 2 (OMIM #605275) and susceptibility to Schwannomatosis (OMIM #615670)." (PMID 37509153, 2023). "LZTR1 functions as a component of the CUL3 E3-ligase complex, which mediates the degradation of RAS and is a tumor suppressor gene that can cause schwannomatosis and Noonan syndrome." (PMID 35706047, 2022). "Multiple tumors are a hallmark of neurofibromatosis type 1(NF1) and related forms, NF2-related-schwannomatosis (formerly NF2) or SMARCB1/LZTR1-related schwannomatoses." (PMID 35741273, 2022). "In this article, we report a patient with dual diagnosis, LZTR1‐related Schwannomatosis and 7q11.23 duplication syndrome who presented with incidentally discovered painless schwannomatosis along the spinal nerves." (PMID 33269527, 2021). "Comprehensive genetic testing with gene panel and chromosomal microarray led to a dual diagnosis of LZTR1 related schwannomatosis and 7q11.23 duplication syndrome." (PMID 33269527, 2021). "Spinal schwannomas, increased severity of pain and reduced penetrance were seen more commonly in LZTR1‐related schwannomatosis than in SMARCB1‐related tumors." (PMID 33269527, 2021). "Until recently, the presence of vestibular schwannoma excluded a diagnosis of schwannomatosis but patients with SMARCB1 and LZTR1 pathogenic variants that met neurofibromatosis type 2 (NF2) criteria have been described." (PMID 32575496, 2020). "The vast majority of these tumors are sporadic, with the remainder arising as a result of the genetic syndrome Neurofibromatosis Type 2 or, more rarely, LZTR1-related schwannomatosis." (PMID 32642684, 2020). "Pathogenic variants (PVs) in LZTR1 or SMARCB1 are detected in approximately 86% of familial and ∼40% of sporadic schwannomatosis cases utilizing standard clinical mutation analysis including exons and intronic segments at exon boundaries (typically ± 20 nucleotides)." (PMID 40794298, 2025). "The identification of LZTR1 in 2014 as a cause of the related schwannomatosis condition (multiple schwannomas but a lack of meningiomas, VS and ependymoma) resulted in significant clinical overlap between NF2-SWN and LZTR1-SWN." (PMID 41160189, 2025). "Schwannoma could co-occur when the tissues attain additional hits in schwannomatosis-related genes (e.g., LZTR1)." (PMID 39857711, 2025). "This variant has been detected over 160 times in this clinical cohort and has neither been identified with other germline pathogenic LZTR1 variants nor in an individual reporting features of Noonan syndrome or Schwannomatosis." (PMID 41300834, 2025). "Exome analysis showed that patient 2 harbors a germline LZTR1 p.Arg68Gly variant, while patient 1 has no schwannomatosis-related mutations." (PMID 39857711, 2025).
schwannomatosis (continued). "Interestingly, only one reported case in the cohort of patients with schwannomatosis was characterized by a genomic deletion of the entire LZTR1 gene, c.1-?2523+?del." (PMID 39062695, 2024). "Patients with SMARCB1- and LZTR1-associated schwannomatosis often develop multiple painful non-vestibular schwannomas in the absence of meningiomas or other tumor types." (PMID 37821623, 2023). "There is also a possibility that at least a proportion of the schwannomatosis cases that remain genetically unexplained might be caused by a variant within NF2, SMARCB1, or LZTR1 that has been missed by routine diagnostic methods." (PMID 35723634, 2022). "Since this frequency of LZTR1‐associated schwannomatosis (1/1203) is not observed this suggested that LZTR1 carries a lower risk of disease than a typical autosomal dominant gene." (PMID 35391499, 2022). "The most common schwannomatosis‐associated gene is NF2, but SMARCB1 and LZTR1 are also associated." (PMID 35723634, 2022). "Analysis of SMARCB1 variant-negative schwannomatosis patients led to the discovery of LZTR1 variants in 2014." (PMID 35698239, 2022). "The molecular mechanisms by which inactivation of the LZTR1 or SMARCB1/INI1 gene in addition to the NF2 gene causes schwannomatosis are not understood." (PMID 34604034, 2021). "Additionally, recent evidence indicates that LZTR1-mutant schwannomatosis schwannomas exhibit deregulated VEGF receptor, ErbB3, and ERK signaling." (PMID 34604034, 2021). "In a total of 247 identified LZTR1 variants, there were no single or multiple exon deletions, and no whole-gene deletions, identified in patients fulfilling schwannomatosis criteria." (PMID 33879870, 2021). "Even if the presence of cutaneous Cal spots is included among clinical signs in Rasopathies, until now they are not considered a typical sign of schwannomatosis due to LZTR1 pathogenic variants." (PMID 32575496, 2020). "The LZTR1 gene has been found to be involved in the development of schwannomatosis." (PMID 31044557, 2019). "So far, two schwannomatosis predisposition genes have been identified, SMARCB1 and LZTR1." (PMID 27921248, 2017). "Schwannomatosis-associated LZTR1 mutations were found in nearly all exons; thus, no positional preference of mutations was observed." (PMID 27921248, 2017). "Taken together, we surmise that it is unlikely that unidentified somatic mosaicism for SMARCB1 or LZTR1 mutations would account for the high number of sporadic schwannomatosis cases without identified mutations." (PMID 27921248, 2017). "Such a high rate of LZTR1 mutation in SMARCB1 mutation-negative schwannomatosis patients was not, however, observed in subsequent studies." (PMID 27921248, 2017). "Mosaicism for somatic LZTR1 or SMARCB1 mutations in patients with schwannomatosis has not so far been reported and only one case of germline (gonadal) mosaicism for a SMARCB1 mutation has been identified." (PMID 27921248, 2017). "So far, patients with schwannomatosis and LZTR1 germline mutations have not been reported to exhibit meningiomas, in contrast to patients with SMARCB1 germline mutations." (PMID 27921248, 2017). "Recently, a new Schwannomatosis gene, LZTR1, has been discovered." (PMID 25739810, 2015). "However, it can also present as multiple lesions, particularly in association with syndromes such as neurofibromatosis type-2 and schwannomatosis, which are linked to genetic mutations in the NF2 gene and the tumor suppressor genes SMARCB1 and LZTR1, respectively." (PMID 40575212, 2025). "Germline LZTR1 variants are reported in Noonan syndrome, which can be either autosomal dominant (Noonan syndrome 10, #MIM 616564) or autosomal recessive (Noonan syndrome 2, #MIM 605275), and are also associated with susceptibility to schwannomatosis (#MIM 615670)." (PMID 39062695, 2024). "Moreover, known VS predisposing conditions, NF2-related schwannomatosis and LZTR1-related schwannomatosis, were not used as exclusionary criteria for cases." (PMID 36546557, 2023).
schwannomatosis (continued). "However, many LoF LZTR1 variants exist in Genome Aggregation Database (gnomAD) in people who do not have clinical symptoms of schwannomatosis." (PMID 35391499, 2022). "We have also recognised that in an era of increasing large gene panel testing, exome and genome screening that ‘incidental’ presumed pathogenic variants in particular in LZTR1 will be identified in individuals with no family history or suggestive personal history of schwannomatosis." (PMID 35361920, 2022). "Furthermore, many sporadically affected individuals that do not have either LZTR1 or SMARCB1 germline pathogenic variants but meet schwannomatosis criteria, have mosaic NF2 with identical pathogenic variants in two separate schwannomas." (PMID 35361920, 2022). "Additionally, evidence of pathogenicity for schwannomatosis‐associated LZTR1 variants should not rely solely on interpreting the germline LZTR1 variants, but also on analysis of the tumor DNA when available." (PMID 35391499, 2022). "However, schwannomas have not been reported in people with this deletion and whole-gene deletions have not been reported in LZTR1-associated schwannomatosis." (PMID 33879870, 2021). "However, some patients with schwannomatosis do not have LZTR1 or SNF5/SMARCB1/INI1 mutations, suggesting the presence of another tumor suppressor gene on chromosome 22q in schwannomatosis development." (PMID 34604034, 2021). "Furthermore, although INI1/SMARCB1 and LZTR1 mutations show strong correlation with schwannomatosis, there is no direct evidence for their role in Hippo pathway signaling." (PMID 32960816, 2020). "Furthermore schwannomatosis predisposition genes are likely to exist since germline mutations in SMARCB1 or LZTR1 are not detectable in at least 50% of sporadic patients with schwannomatosis (Kehrer‐Sawatzki, Farschtschi, Mautner, & Cooper, 2017)." (PMID 29779243, 2018). "Alternatively, somatic mosaicism for SMARCB1 or LZTR1 mutations could be responsible for the relatively high proportion of sporadic schwannomatosis patients without detectable germline SMARCB1 and LZTR1 mutations." (PMID 27921248, 2017). "The three major schwannomatosis genes, NF2, LZTR1 and SMARCB1, are all located within approximately 9 megabases on chromosome 22 and cause three genetically distinct conditions with significant clinical phenotypic overlap." (PMID 41284083, 2025). "Furthermore, functional characterization of known causative variants for schwannomatosis will undoubtedly advance our understanding of potentially new mechanisms of disease in schwannomatosis, particularly for variants located in noncoding regions of both SMARCB1 and LZTR1." (PMID 35723634, 2022). "Here we demonstrate the clinical overlap of NS, schwannomatosis and NF1 and support the inclusion of LZTR1 in gene panels for NS." (PMID 35840934, 2022). "By contrast, schwannomas from LZTR1-unrelated schwannomatosis patients, as well as patients with NF2, showed diffuse but positive LZTR1 immunostaining." (PMID 27921248, 2017). "In a proportion of schwannomatosis patients without identifiable germline LZTR1 or SMARCB1 PV, somatic 22q LOH has been detected in schwannomas with or without an identifiable somatic NF2 PV." (PMID 40794298, 2025). "Whole-exome sequencing with the genomic DNA from peripheral blood leukocytes showed that patient 1 with INF2 p.Gly73Asp had no germline, schwannomatosis-related gene variants including 22q loss of heterozygosity (LOH), NF1, NF2, LZTR1, SMARCB1, and COQ6." (PMID 39857711, 2025). "Segmental schwannomatosis has been seen in approximately one third of non-NF2-related schwannomatosis, but these cases have not generally been associated with identifiable SMARCB1 or LZTR1 mosaic variants." (PMID 41284083, 2025). "However, people with LZTR1-related schwannomatosis can have unilateral vestibular schwannomas and people with SMARCB1-related schwannomatosis can develope meningiomas." (PMID 40510571, 2025).
schwannomatosis (continued). "Differential diagnosis of schwannomatosis can be difficult in patients, especially if they are oligosymptomatic and testing for SMARCB1 and LZTR1 germline mutations is negative." (PMID 32443592, 2020). "A new gene, LZTR1, located at 22q11.21 and centromeric to SMARCB1 has been recently reported to be mutated in ~80% of Schwannomatosis patients negative for SMARCB1 mutation." (PMID 25739810, 2015). "However, many patients and families with schwannomatosis do not have identifiable germline variants in NF2, SMARCB1, LZTR1, CDKN2A, or DGCR8, and efforts have been underway to identify other responsible molecular drivers of schwannoma predisposition." (PMID 37821623, 2023). "Finally, one patient (Family ID 219) with a clinical diagnosis of Schwannomatosis and negative for mutations in NF2, LZTR1, and SMARCB1 is under investigation for a somatic mosaicism in NF2." (PMID 31370276, 2019). "SMARCB1, LZTR1, and NF2 clearly function as classical tumour suppressor genes, and hence, it is not unreasonable to suppose that other schwannomatosis predisposition genes might also act in an onco-suppressive manner." (PMID 27921248, 2017). "Schwannomatosis not related to NF2 can result from mutations in tumor suppressor genes on chromosome 22 including but not limited to the SWI/SNF-related BAF chromatin remodeling complex subunit B1 (SMARCB1) and leucine zipper like post-translational regulator 1 (LZTR1 genes; Tamura, 2021)." (PMID 41001135, 2025). "Exploration of the possible interactions of potential candidate genes for schwannomatosis with the known causative genes, might provide some insight into the type and location of novel PVs in cases where no variants in SMARCB1, LZTR1, or NF2 have been identified." (PMID 35723634, 2022). "However, an intriguing aspect of LZTR1‐related schwannomatosis is that despite recorded nonpenetrance in schwannomatosis families with an apparent pathogenic/likely pathogenic variant a relatively high number of relatives do develop schwannomas (50% in Manchester)." (PMID 35391499, 2022). "Consequently, 27% of sporadic schwannomatosis patients who do not exhibit germline NF2, SMARCB1, and LZTR1 mutations, but who do display tumour-specific biallelic NF2 inactivation, could, in principle, be caused by mutations in hitherto unidentified gene(s)." (PMID 27921248, 2017). "In many studies assessing the clinical symptoms of patients with schwannomatosis (SWN), no strict distinction was made between LZTR1-related or SMARCB1-related or any other type of non-NF2-related SWN." (PMID 40794298, 2025). "In this study, we performed extended genetic screening of 75 unrelated schwannomatosis patients without identified germline PVs in NF2, LZTR1, or SMARCB1." (PMID 35723634, 2022).
Noonan syndrome (57 papers, 2019 to 2026). "LZTR1 attenuation resulting from genetic mutations associated with Noonan syndrome, potentiate NOC2L activity leading to reduced apoptosis and a compensatory increase in autophagy." (PMID 41175093, 2026). "Although most cases of Noonan syndrome are inherited in an autosomal-dominant manner, a recessive form has recently been linked to biallelic variants in the LZTR1 gene." (PMID 39860591, 2025). "LZTR1 has complex heritability as primarily an autosomal recessive, loss-of-function disease causing Noonan syndrome but also with rare domain-restricted, dominant-negative variants causing Noonan syndrome in an autosomal dominant fashion." (PMID 41300834, 2025). "The positively selected Ile500 mutants promoted a stimulus-dependent upregulation of ERK phosphorylation, in a manner similar to the dominant Noonan syndrome-associated LZTR1 mutant." (PMID 39116879, 2024). "We identified a total 51 patients with variants in LZTR1 and a clinical diagnosis of Noonan syndrome; of these, 28 are female and 20 are male, while for 3 patients, the sex was not reported." (PMID 39062695, 2024). "Autosomal dominant (AD) mutations in LZTR1 have been identified in patients with Noonan syndrome (NS), a congenital anomaly syndrome." (PMID 39352760, 2024). "Gene variants in LZTR1 are implicated to cause Noonan syndrome associated with a severe and early-onset hypertrophic cardiomyopathy." (PMID 38333672, 2024). "Most cases of Noonan syndrome are inherited in an autosomal dominant manner; however, among the known variants, only those caused by LZTR1 pathogenic variants can be inherited as either autosomal dominant or autosomal recessive." (PMID 39831200, 2024). "Loss-of-function mutations in LZTR1 increase the risk of being affected by Noonan syndrome (MIM:605,275) and an inherited disorder of multiple schwannomas." (PMID 36833427, 2023). "We report a pair of dichorionic diamniotic (DCDA) twin pregnancy affected by Noonan syndrome (NS) with a novel mutation of LZTR1 determined by genetic analysis." (PMID 36609239, 2023). "Mutations of LZTR1 were identified in Noonan syndrome patients with bleeding disorders, and these mutations led to defects in LZTR1-mediated ubiquitination of CHMP1B and, ultimately, impaired vesicle trafficking, resulting in cardiovascular dysfunction." (PMID 35327608, 2022). "There is also a need to clarify the overlap with allelic conditions such as LZTR1-related Noonan syndrome as well as Coffin-Siris and rhabdoid tumour predisposition with SMARCB1 variants." (PMID 35361920, 2022). "Inactivating germline mutations in LZTR1 are associated with Noonan syndrome and functional studies have linked LZTR1 inactivation to RAS ubiquitination, increased RAS-MAPK signaling, and cell proliferation." (PMID 35197475, 2022). "Noonan syndrome -causing LZTR1 variants have been reported in the literature both in homozygous and heterozygous forms, depending on the variant." (PMID 35739278, 2022). "Here we report a Chinese family with Noonan Syndrome caused by a heterozygous variant in LZTR1, which will change the previous understanding of LZTR1 inheritance and improve our understanding of Noonan Syndrome." (PMID 33407364, 2021). "LZTR1 mutations have also been associated with Noonan syndrome (NS), a type of RASopathy affecting multiple organ systems, including growth, craniofacial, cardiovascular, and neurocognitive abnormalities." (PMID 34222248, 2021). "Variants in LZTR1 are associated with Noonan syndrome, which is a genetic disorder that causes multiple congenital abnormalities and characteristic facial features that evolve with age." (PMID 33895855, 2021).